ERBB2 (erb-b2 receptor tyrosine kinase 2)
Diseases named in the same sentence as ERBB2 in open-access papers (continued):
Sharing a sentence is not in itself a finding about the gene and the disease.
cancer (continued). "Targeting Wdr5 in chemotherapy or trastuzumab reduces ErbB2 overexpression and inhibits cancer cell growth." (PMID 40426980, 2025). "Discovering ERBB2 i14e as a novel isoform of ERBB2 has mechanistically shed lights on cancer cell proliferation and drug resistance, pointing to a diagnostic biomarker and therapeutic target for GBC." (PMID 39948369, 2025). "The expression of the ERBB2 gene was found to be higher in BC compared to other cancers, with the expression patterns illustrated." (PMID 40177517, 2025). "For example, ERBB2 was exclusively expressed in cluster 3, which corresponded to the “in-situ cancer” region in the pathologist’s annotations." (PMID 40905789, 2025). "In HER2-positive cancers, amplification of the ERBB2 locus leads to marked overexpression of the HER2 receptor, driving constitutive activation of downstream cascades (PI3K/AKT and MAPK) that promote proliferation, survival, and apoptosis resistance." (PMID 41228310, 2025). "The most prevalent aberrations of HER2 in cancer are HER2 protein overexpression and ERBB2 gene amplification, present in 15–20% of breast and gastroesophageal adenocarcinomas." (PMID 40770324, 2025). "Studies performed on both the cancer cell panel and mixed ERBB2+/ERBB2− cultures demonstrated that pre-treatment with 929-B6 enhanced ERBB2-specific infectivity for lentiviral vectors pseudotyped with either VSV-G or VSV-Gmut + 929R." (PMID 41472234, 2025). "Growing evidence suggests that YWHAZ is often overexpressed across numerous cancer types and acts as an oncogene by promoting cellular processes such as proliferation, migration, and invasion through interactions with ErbB2 and p85." (PMID 41487287, 2025). "ERBB2 amplification is a more commonly observed alteration event which is associated with overexpression of HER2 protein, triggering oncogenesis and uncontrolled cell growth through PI3K/AKT/mTOR and MAPK signaling pathways in many cancers." (PMID 40098704, 2025). "Genetic biomarkers can be applied across multiple cancer types, e.g., HER2 (ERBB2) amplification, and the first genetic biomarker to be used in a cancer agnostic approach was NTRK fusions (Neurotrophic tyrosine receptor kinase)." (PMID 40806432, 2025). "We compared the prevalence of ERBB2 alterations detected in patient-matched tissue and liquid biopsies in select cancers." (PMID 40178042, 2025). "Genomic profiling has identified ERBB2 amplification and mutations, encoding overexpressed or hyperactivated HER2, and ERBB3 (encoding HER3) alterations as drivers of human cancers." (PMID 40178042, 2025). "Despite the availability of various CMC cell lines, most represent triple-negative orepidermal growth factor receptor 2 (ErbB2)-enriched subtypes, which limit research on hormone receptor-positive cancers." (PMID 40689167, 2025). "We assessed the presence of activating ERBB2 alterations across 83,332 solid tumors in the Memorial Sloan Kettering Cancer Center (MSKCC) clinicogenomic cohort." (PMID 40178042, 2025). "Collectively, these experimental findings demonstrate that ERBB2 i14e protects cancer cells from trastuzumab binding, leading to resistance to trastuzumab therapy." (PMID 39948369, 2025). "In a recent meta-analysis, cTns were identified as a predictive marker for the development of cancer therapy-related LV dysfunction in patients receiving various regimens of cytotoxic chemotherapy and/or ERBB2 inhibitor therapy." (PMID 39953627, 2025). "This vaccine has demonstrated potential in generating a strong immune response by inducing T-cell activation against the ERBB2 antigen, a promising strategy for improving anti-cancer immunity." (PMID 40160263, 2025).
cancer (continued). "This study highlights ERBB2 alterations across diverse cancers, demonstrating their heterogeneity and clinical significance." (PMID 40828885, 2025). "ERBB2 activation arises from gene amplification and overexpression and plays a well-established role in cancers such as breast, gastric, and endometrial carcinomas." (PMID 41008893, 2025). "The results also suggest similarities between urothelial and esophagogastric cancers, a cancer type in which ERBB2 heterogeneity and selection for ERBB2 wildtype subclones has been shown to be a common mechanisms of resistance to HER2-directed therapies." (PMID 41422272, 2025). "Of particular note is a small core of microRNA-regulated proteins, which also represent important nodes in altered functions in cancer, including ErbB2, NFkB1, and Notch2." (PMID 40004024, 2025). "According to previous works, trastuzumab resistance is mainly attributed to genetic and epigenetic alterations in cancer that are responsible for the aberrant constitutive activation of the ErbB2 pathway." (PMID 39786928, 2025). "Among the validated substrate candidates are the cancer-related ERBB2 as well as the immune system-related CD2, CD68, and CD86." (PMID 40593564, 2025). "HER2, encoded by the ERBB2 gene, is a receptor tyrosine kinase frequently activated in human cancers via gene amplification, mutation, and/or protein overexpression." (PMID 41422272, 2025). "With an ORR of 29.4% and a disease control rate of 75.5% across various cancers, this study supports a broader application of ErbB2-directed treatments." (PMID 39908697, 2025). "Given that these subpopulations occur relatively infrequently, at approximately 7% of the total population, identifying differences in cell cycle regulation, especially in terms of ErbB2 expression, is critical for improving cancer treatment." (PMID 41161384, 2025). "The inhibition of ERBB2 signalling has been shown to disrupt cell cycle progression and hinder angiogenesis, demonstrating its potential as a therapeutic target in cancer treatment." (PMID 39063109, 2024). "Cases with ERBB2-positive cancer are treated with ERBB2-targeted antibodies or utilization of small-molecule inhibitor treatment in conjunction with chemotherapy." (PMID 38563878, 2024). "Other cancers exhibit increased expression of the transmembrane glycoprotein HER2 (also known as Erbb2), which has a molecular weight of 185 kDa." (PMID 38496894, 2024). "Most of the therapeutic target genes were exclusively expressed on functionally heterogeneous cancer cells, with the exception of ERBB2 expression in collecting duct principal cells of normal renal epithelium." (PMID 38944814, 2024). "Numerous epidermal growth factors, including the receptor tyrosine protein kinase ErbB2/HER2, exhibit upregulation during cancer development." (PMID 38542836, 2024). "In our cohort, ERBB2 amplification was more prevalent compared to missense alterations, consistent with observations in other cancer types." (PMID 39410541, 2024). "A recent study in multiple cancer types reported that ERBB2 mRNA OE (33.3%) was much more common than cases with IHC-positive (9.3%) and amplification (4.1%)." (PMID 39931207, 2024). "The discovery of gene fusions involving Neuregulin-1 (NRG1) within solid tumors has important therapeutic implications, as they are being actively explored as targets for emerging ERBB/ERBB2/ERBB3-directed anti-cancer agents." (PMID 39575425, 2024). "HSP90B1, a member of the HSP90 family, plays a role in sustaining cancer cell survival by facilitating ERBB2-dependent downstream signalling pathways." (PMID 39063109, 2024). "Consistent with previous reports, canonical cancer gene mutations in EGFR, ERBB2, and BRAF were always truncal as early as the AAH/AIS stage, suggesting that these mutations are very early genomic events before the acquisition of invasiveness." (PMID 38764572, 2024).
cancer (continued). "Studies have recently shown, for example, that ERBB2‐mutant cancers are sensitive to antibody–drug conjugates (trastuzumab deruxtecan)." (PMID 38287892, 2024). "Their robustness makes them indispensable tools in the detection of a wide array of biomolecules, such as c-erbB2, HER2, DNA, and RNA, which are crucial in the early diagnosis of virus-related diseases and cancers." (PMID 38542577, 2024). "Consistent with a rationale for indirect targeting of ERBB3 by blocking ERBB2, responses to ERBB2 drugs have been observed in the clinic in patients with ERBB3 mutant cancers." (PMID 38806620, 2024). "In particular, ERBB3 has been proposed to be the preferred dimerization partner for ERBB2, and to critically contribute to ERBB2-mediated transformation in breast and other cancer types." (PMID 38806620, 2024). "In pancreatic ductal adenocarcinoma (PDAC), cancer-associated fibroblasts (CAFs) secrete NRG1, which activates ERBB2 and ERBB3 receptor tyrosine kinases." (PMID 38957319, 2024). "A major strength of this study is the use of a very large scale genetic study to identify many new genetic loci contributing to ERBB2-driven cancers." (PMID 39067134, 2024). "We evaluated the genetic alteration status of ERBB2 across a panel of 32 cancers on the GDC Data Portal website." (PMID 39409883, 2024). "FDA-approved medications for other cancer types can be used to treat PIK3CA mutations, ATM, ERBB2, and ERBB2 amplifications." (PMID 39759612, 2024). "Increased Cpt1a activity enables cancer cells to utilize FAs as an energy source, bypassing the reliance on ErbB2 signaling for growth and survival." (PMID 39097623, 2024). "ErbB receptors, especially EGFR and ErbB2 have been the primary choices as targets for developing cancer therapies." (PMID 39193326, 2024). "More indirect targeting of the potently transforming heterodimeric complex of ERBB3 with ERBB2 (with anti-ERBB2 drugs or compounds such as bispecific ERBB3/ERBB2 antibodies) provides another route for activity against ERBB3-driven cancer." (PMID 38806620, 2024). "This was also the case when treating mixed cultures of EGFR- and ErbB2-expressing cancer cells that served as a model for heterogeneous target antigen expression, which is often observed in solid tumors and can contribute to their escape from immunotherapy." (PMID 38334638, 2024). "In this regard, we interrogated the downstream disease targets that are associated or linked to HER2/erythroblastic oncogene B receptor tyrosine kinase 2 (ERBB2), and we evaluated the frequency of genetic alterations of ERBB2 in PC compared to other cancers." (PMID 39409883, 2024). "Trastuzumab (Trz) was the pioneering monoclonal antibody designed to combat cancer by inhibiting the ErbB2 pathway." (PMID 38542836, 2024). "For example, in the case of insufficient effects of ERBB2 inhibition due to the compensatory overexpression of the EGF receptor (EGFR) in cancer cells, administration of the ERBB2 inhibitor, Herceptin, is often combined with suppressing EGFR activity." (PMID 39769257, 2024). "Since malignancies are linked to overexpression of the human ErbB2 gene—which codes for the human EGFR, often known as HER2—id, the connection between ErbB2/HER2 and cancer has also been detected in humans." (PMID 39031216, 2024). "Given that across all cancers, somatic ERBB3 mutations occur at a frequency of 2.1%, these findings support a rationale for treating cancers with these alterations with kinase inhibitors and/or therapeutic antibodies targeting ErbB2/ErbB3." (PMID 39120280, 2024).
cancer (continued). "ERBB2 (HER2) expression decreased in cancer cells co-cultured with Nw-PA-T (RQ=0.064, p ≤ 0.001) and Nw-MA-T (RQ=0.436, p ≤ 0.001), this expression continued to decrease in Ob-PA-T (RQ=0.039, p ≤ 0.001, p2<0.05) and Ob-MA-T (RQ=0.127, p ≤ 0.001, p3<0.01)." (PMID 39072314, 2024). "Fifteen to 20% of BC cases are ERBB2-positive (formerly known as HER2-positive), characterized by cancer cells containing high levels of the ERBB2 protein." (PMID 38516198, 2024). "Initially, YBX1 was found to transcriptionally activate the expressions of ABCB1, an ATP-binding cassette transporter associated with multidrug resistance, as well as the growth factor receptor genes EGFR and HER2/ErbB2 in cancer cells." (PMID 38254206, 2024). "Meanwhile, MTOR was found to be linked to PIK3C; BRAF and MAPK1 were found to be linked to EGFR; and ERBB2 and ALK are linked to the common NSCLC and Cancer pathway." (PMID 38921583, 2024). "The effect on the target EGFR/ERBB2 and AKT/PKB pathways was confirmed by up-/downregulated proteins that are part of these pathways and that further implicated the whole range of cancer enabling hallmarks." (PMID 39268460, 2024). "Peiffer et al29 evaluated ERBB2-low in a large retrospective group of patients using the National Cancer Database." (PMID 38517439, 2024). "Further investigations have revealed that activated ErbB2 stimulates the expression of GLS in cancer cells through the PI3K/Akt-independent nuclear factor-kappa B (NF-kB) pathway in breast and gastric cancer." (PMID 38459595, 2024). "Somatic ERBB2 alterations are typically rare, occurring in only a small percentage of cancer cases (1–3%) across various types of cancer." (PMID 39335117, 2024). "The ERBB2 expression appeared to be similar between HER2 0+ and 1+ carcinomas, as well as between 2+ NA, DE, and 2+ WA carcinomas." (PMID 38893129, 2024). "ERBB2 3’UTR-destabilizing constructs induced increased caspase 3 in the trastuzumab-resistant ERBB2+ cancer cells." (PMID 37359373, 2023). "In the present study, we aimed to rationally design safe anti-cancer chimeric proteins against ErbB2-positive tumor cells through computational approaches." (PMID 36936983, 2023). "ERBB2-positive cancers are currently defined as those with high expression (3+) via IHC or ERBB2 amplification via ISH." (PMID 36821125, 2023). "The main outcomes were cumulative incidence and hazard rate of CBC in the entire study population and in subgroups divided by cancer subtype, categorized according to hormone receptor (HR) and ERBB2 status." (PMID 38100108, 2023). "Rarely, SB-PCCs showed high microsatellite instability, mutations in IDH1 and ERBB2 genes, or FGFR2 amplification (one case each), which are established or promising therapeutic targets in such aggressive cancers." (PMID 36812376, 2023). "HER2 overexpression and/or ErbB2 gene amplification or aberrant transcription results in an up to a 100-fold increase in cancer cell surface HER2 and consequently drives HER2-mediated tumorigenesis." (PMID 36761943, 2023). "GSEA revealed that, compared with KC mice, KSC mice had an enrichment in stem cell networks (ESC pluripotency, Wnt, Notch, Hedgehog); EMT; a pancreatic ductal cell program; cancer-associated networks; and EGFR, ERBB2/HER2, and MET signaling pathways." (PMID 37643018, 2023). "Because of the overexpression of the oncogene ERBB2, HER2+ promotes the growth of cancer cells, which results in positive progress and a worse prognosis." (PMID 37228493, 2023).
cancer (continued). "This ligand-binding induces receptor heterodimerization with ERBB2, causing the activation of the PI3K and MAPK pathways, which results in increased cell proliferation/migration and resistance to apoptosis in cancer." (PMID 37958963, 2023). "A higher rate of ERBB2-low disease was seen in hormone receptor–positive cancers (TNBC, 51.5% for ERBB2-low compared with 58.6% for ER-negative, PR-positive cancers; 66.1% for ER-positive, PR-negative cancers; and 69.1% for ER-positive, PR-positive cancers)." (PMID 36821125, 2023). "Mutations responsible for abnormal activation of genes encoding RTKs, such as EGFR, HER2/ErbB2, and MET, have been identified in various cancer types." (PMID 38203502, 2023). "For patients with ERBB2-positive cancer, the proportion in China (30.2%) was higher than that in the US (15.6%)." (PMID 37389867, 2023). "The drug response profiles observed in all three FMOC02 PDCs were remarkably similar and showed continued dependency of cancer cells on the ERBB2/EGFR and RAS/ERK signalling." (PMID 36476658, 2023). "We have shown that in certain genetic settings of cancer as in ERBB2 HCT116, we are superior to CRISPR, RNAi, and shRNA in a head-to-head comparison." (PMID 37359373, 2023). "This biomarker of attenuation of erbB2 phosphorylation in redirected cells was used to establish cancer cell redirection for in vitro models." (PMID 36765535, 2023). "We next evaluated the potential impact of high-level ERBB2/HER2 mRNA expression on cancer-related mortality (CRM) in 716 evaluable MM patients." (PMID 37373090, 2023). "desARE3’UTR ERBB2-30 is effective as desARE3’UTR ERBB2-1 and -3 in degrading ERBB2 across multiple ERBB2 cancer types." (PMID 37359373, 2023). "Within 4 days, we observed by immunofluorescence that ERBB2 protein (stained green) expression has been significantly decreased in the cancer cells containing the destabilizing elements compared to the wildtype and vector control." (PMID 37359373, 2023). "This means that the designed selected CPs are capable of being enternalized by ErbB2 into the cell where their ribosome inactiving activity can be of assistance for cancer therapy." (PMID 36936983, 2023). "Combining a cytostatic drug with an inhibitor of receptors overexpressed in cancers, such as the receptor tyrosine kinase ErbB2 (or Her2/Neu), also results in greater antitumor efficacy in vivo." (PMID 38004619, 2023). "Of these, 69% of patients with ERBB2 (formerly HER2 or HER2/neu)-positive cancer received trastuzumab-based therapy after 2017 in China compared with 62% of patients in the US during the same period." (PMID 37389867, 2023). "Some variants, including BRAF V600E, the copy number variation of ERBB2, PTEN A121E and R161*, are associated with >10 cancer indications and form hubs of the network." (PMID 36856726, 2023). "A MMTV-neu mouse model, expressing an unactivated form of rat Erbb2 gene (homolog of HER2), is similar to human cancers, characterized by long latency (29–48 weeks)." (PMID 36831460, 2023). "In contrast, the CD19-4D5scFv redirected CD19scFv-CAR T cells kill the healthy fibroblasts only in presence of more than 100 ng/mL fusion protein, which is 100-fold higher than the ED50 for ErbB2 cancer cell killing." (PMID 36672182, 2023). "We found that the 3’UTR of ERBB2 in only ERBB2-expressing cancer cells MCF7, BT474, and T47D is enriched with UUUUUU sequences which are mRNA-stabilizing elements." (PMID 37359373, 2023). "According to another observation, ErbB2 also localizes to the mitochondria in cancer cells via mtHSP70." (PMID 37109525, 2023). "ErbB2 belongs to ErbB receptor family and its receptor signalling pathway is capable of promoting metastatic activities in cancer." (PMID 37277696, 2023). "Accordingly, the ErbB2-CAR T cells with the 4D5scFv killed the ErbB2low fibroblasts from the healthy donors with nearly the same efficiency as the SKOV-3 cancer cells with high ErbB2 levels." (PMID 36672182, 2023).